IL6 (interleukin 6)
Diseases named in the same sentence as IL6 in open-access papers (continued):
Sharing a sentence is not in itself a finding about the gene and the disease.
depression (continued). "Produced by both immune and non-immune cells, like tumor cells and tumor-associated macrophages (TAMs), IL-6 is one of the key biomarkers of depression." (PMID 30042700, 2018). "Maternal stress and depression have both been associated with higher circulating levels of IL-6 and TNF-α across pregnancy." (PMID 30200631, 2018). "Clinical and preclinical settings often associate chronic stress exposure with major depressive disorders and enhanced pro-inflammatory cytokine levels, most consistently IL-1β and IL-6." (PMID 30142161, 2018). "The patient of this study had normal urinary IL-6 values despite ongoing depression and fatigue, both of which are usually associated with enhanced IL-6 levels in breast cancer survivors." (PMID 30546293, 2018). "In terms of immune dysregulation, depression has been associated with both immune activation (increase in pro-inflammatory mediators such as IL-6, TNF-α, CRP, IL1) and immune suppression (loss of T cell and NK cell function) (reviewed)." (PMID 29894487, 2018). "The results are also consistent with previous longitudinal studies showing an association between adult depression, higher IL-6 levels in childhood and in adulthood." (PMID 29140226, 2018). "We have previously reported that patients with elevated serum IL-6 levels early during a stroke have an elevated risk for post-stroke depression, suggesting that IL-6 is associated with the incidence of depression." (PMID 29856741, 2018). "From the physical health viewpoint, depression in the elderly was found to be associated with increased levels of proinflammatory cytokines including interleukin- (IL-) 1B and IL-6." (PMID 30596085, 2018). "We also investigated the effect of CVS on the concentration of major cytokines associated with depression, i.e., IL-1β, IL6, and TNF-α in the blood of rats." (PMID 30533439, 2018). "Depression has therefore been associated with high levels of IL-6, TNF-α, IL-1 beta, C-reactive protein (CRP), chemokines, and adhesion molecules." (PMID 29619128, 2018). "Interleukin 6 (IL-6) levels are commonly elevated in patients with depression and psychosis and in people who are at risk of developing these disorders." (PMID 29197507, 2018). "The polymorphism rs1800795 in the IL-6 promoter gene is a genotype that overproduces IL-6, which has been associated with depressive disorder." (PMID 30662368, 2018). "DNMT1 methylates intronic sequences of interleukin 6 (IL-6) genes, reducing level of this pro-inflammatory cytokine which has previously been implicated in the development of depressive disorders." (PMID 30154441, 2018). "Population-based longitudinal studies reported associations of higher serum IL-6 with future risks for depression and psychosis." (PMID 29163240, 2017). "In concordance, high levels of circulating IL-6 are strongly associated with stress, depression, and autoimmune disease." (PMID 28491039, 2017). "Our finding that antidepressant use had opposing associations with IL6 methylation compared to that of depression is particularly interesting, given the previous observations that antidepressants are effective in reducing elevated IL6 levels in MDD." (PMID 29070016, 2017). "Depression has been linked to a pro-inflammatory response, because cytokines like interleukin 6 (IL-6) and tumor necrosis factor alpha (TNF) are increased." (PMID 29403374, 2017). "Depression was associated with a 2.4% decreased IL6 methylation while antidepressant use was associated with a mean 4.6% increase in methylation." (PMID 29070016, 2017). "The higher pre-treated blood concentration of IL-6 was the risk factor of the development of major depressive disorder but sleep disturbances was followed by depressive symptoms." (PMID 26649857, 2017). "Depression in HF component of HRV reported during systemic administration of endotoxin to rats is associated with increased cytokine production (IL-6)." (PMID 28727839, 2017).
depression (continued). "In the multiple imputation dataset the association between IL-6 and hypomanic symptoms remained after additional adjustment for depression (OR for top third compared with bottom third 1.70, 95% CI 1.03–2.81, p = 0.038)." (PMID 27476619, 2017). "IL6 appears to be one of the most robust inflammatory markers associated with depression, and elevated levels have been observed in older individuals with new depressive episodes." (PMID 29070016, 2017). "Data from the Avon Longitudinal Study of Parents and Children (ALSPAC), a UK general population birth cohort, recently showed that higher serum levels of interleukin-6 (IL-6) in childhood is associated with depression and psychosis in young adult life." (PMID 27476619, 2017). "In humans, lower levels of blood DHA were associated to higher IL-6 levels and depression/anxiety scores after an interferon treatment or in healthy young adults." (PMID 28838312, 2017). "Increased IL6 have also been associated with reduced grey matter in the brain, often seen in depression." (PMID 29070016, 2017). "TNF-α, IL-6, and IL-10 also played important roles in depression induced by stress, which caused the increase of proinflammation cytokines, including TNF-α, IL-6, and IL-1β in serum and hippocampus." (PMID 28694833, 2017). "Il-6 has been one of the most investigated ILs due to its high association with depression, though this association is not without dispute." (PMID 27555379, 2017). "We demonstrated that COPD, depression, and COPD with comorbid depression are associated with increased IL-6 levels when compared with healthy controls 42.2 ± 1.87, 40.9 ± 2.12, 41.7 ± 1.31, and 33.2 ± 1.23 pg/ml, respectively (p < 0.05)." (PMID 26403459, 2016). "Compelling evidence exists to suggest elevated levels of IL-6 as both a cause and a consequence of depression." (PMID 28082989, 2016). "Elevation of the proinflammatory cytokine IL-6 has been implicated in depression; however, the mechanisms remain elusive." (PMID 27529677, 2016). "Existing body of research revealed the association between IL-6 and crucial aspects of depression including tryptophan catabolite pathway, melatonin, and neuroprogression as well as central inflammation more broadly." (PMID 26403459, 2016). "Recently, the role of IL-6 in depression was linked to increased IL-6 trans-signaling whereby IL-6 receptor signaling occurs in cells not normally expressing the IL-6 receptor." (PMID 26403459, 2016). "For example, chronically elevated IL-6 levels have been associated with psychological disorder (particularly depression) and changes in immune markers CRP and cortisol have been associated with loneliness longitudinally." (PMID 27367428, 2016). "The data suggest that the association between depression and inflammation seems to be stronger for IL-6 than CRP." (PMID 25877654, 2016). "The risk of developing depression during IFN treatment was found to be dependent on a functional polymorphism in the interleukin-6 (IL-6) gene, rs1800795." (PMID 26821321, 2016). "IL-6 has also been associated to various other diseases, including atherosclerosis, depression, diabetes, and rheumatoid arthritis." (PMID 27153074, 2016). "In conclusion, the functional IL-6 rs1800795 polymorphism in interaction with various stress factors increases the risk of depression and has a greater impact on symptoms measured by the ZSDS." (PMID 26821321, 2016). "Depression is associated with higher levels of IL-1β, IL-6, IFN-γ and TNF-a schizophrenia has been find to exhibit increased concentrations of IFN-γ, IL-2 and IL-6 whereas IL-2, IL-6,IL-8 and IFN-γ were found to be overproduced during BD." (PMID 27598205, 2016). "SNP rs1800795, a functional polymorphism in the promoter of IL6, was reported to increase the risk of stress-17 and interferon treatment-18 induced depression." (PMID 27502736, 2016).
depression (continued). "IL-6 is an important, well-researcher marker of inflammation that has shown a positive association with depression and should be examined in future studies." (PMID 27232630, 2016). "In particular, evidence suggests that depression is associated with increased circulating concentrations of proinflammatory cytokines such as IL-1β, IL-6, TNF-α, and IFN-γ in association with elevations in chemokines and the acute phase protein, CRP." (PMID 26775294, 2016). "Meta-analyses have indicated that the most robust evidence-based inflammatory markers associated with depression include interleukin-6 (IL-6), C-reactive protein (CRP), and TNF-a." (PMID 26617482, 2015). "So far, a positive association between immediate memory impairment and IL-6 level has been reported in other patients, including older people, middle-aged adults and patients with recurrent major depressive disorder." (PMID 25214388, 2015). "C-reactive protein (CRP), tumor necrosis factor- (TNF-α) and interleukin-6 (IL-6) are mediators widely described in worldwide literature have been associated with depression, MCI and diabetes." (PMID 25793613, 2015). "We observed that depression was significantly associated with increased serum IL-6 level in the HSCT patients." (PMID 25922648, 2015). "Analysis of correlations between HADS scores within inflammatory, anti-inflammatory markers and some variables associated with depression showed that HADS score were significantly correlated with serum concentrations of IL-6 and IL-6 / IL-10 (P<0.001)." (PMID 25922648, 2015). "Depression is also associated with aberrant activation of inflammation, such as increases in circulating levels of interleukin (IL)-1β, IL-6, and tumor necrosis factor-α (TNFα)." (PMID 25947540, 2015). "The observed significant increase in sucrose preference in IL6-KO mice, which is indicative of less susceptibility to depression-related anhedonia, confirms an earlier description of enhanced sucrose consumption of IL6-KO mice." (PMID 25760924, 2015). "In conclusion, since IL-6 can affect the outcomes after HSCT and depression was associated with increased serum IL-6 level, early identification of depression can be beneficial in these patients." (PMID 25922648, 2015). "We tried to address this in part, by controlling for the inflammatory biomarkers CRP and IL6 in the multivariable analysis and our results suggest that plasma levels of sVCAM-1 was independently associated with depression symptoms." (PMID 26040277, 2015). "Taken together, the present results suggest that possession of high expression alleles at IL6 and IL1β increase depression risk following interpersonal stress exposure in the present sample." (PMID 25596176, 2015). "First, depression has been positively associated with high systemic levels of inflammatory mediators (especially IL-4, IL-6 and TNF-a), which have underlying pathogenic roles in asthma." (PMID 26197472, 2015). "Severe depression was more strongly associated with IL-6, CRP and TNF-α compared to moderate depression." (PMID 26065825, 2015). "High levels of circulating IL-6 are associated with fatigue and depression among breast cancer patients, and depression is associated with reduced breast cancer survival." (PMID 25305747, 2014). "Inflammatory markers, such as interleukin-6 and C-reactive protein, have also been associated with poorer performance on tests of psychomotor speed and verbal memory in individuals with depression." (PMID 24996486, 2014). "In particular, SLI in basal ganglia and vascular risk factors including higher BMI levels, and inflammation markers, CRP, TNF-α, hs-CRP, and IL-6 can increase the risk for depression." (PMID 24752391, 2014). "IL-1beta has been shown to function synergistically with IL-6 to activate HPA axis to reduce social investigatory behavior and locomotor activity, indicating the underlying combined mechanism of IL-1beta and IL-6 in depression." (PMID 24795767, 2014).
depression (continued). "Changes in Hamilton Depression Rating Scale scores were significantly associated with changes in IL-6 (P = 0.003) levels; changes in Young Mania Rating Scale scores were significantly associated with changes in CRP (P = 0.006) and TNF-α (P = 0.039) levels." (PMID 23826157, 2013). "For example, one of the most consistent biomarkers of depression is elevations in circulating IL-6 and is associated with treatment-resistance." (PMID 23520517, 2013). "On the other hand, several inflammatory cytokines, such as tumor necrosis factor-α (TNF-α) or interleukin-6 (IL-6), have been considered pathogenic factors associated with the mechanism of developing depression." (PMID 24138872, 2013). "Specifically, we found a negative association between selected cellular signalling molecules and dissociation and a positive association for IL-6, similar to published protein data in depression and related disease states by showing." (PMID 23951008, 2013). "It is interesting that those peripheral cytokines that predict emergence of depression after a stroke (e.g., IL-18) differ from the key cytokines typically implicated in depressive illnesses that occur in other circumstances (e.g., IL-6, TNF-α, or IL-1β)." (PMID 23675319, 2013). "Using this approach, our observations reconfirmed dysregulation in two immune genes previously implicated in depression: the cytokines IL-10 and IL-6." (PMID 24143878, 2013). "IL-6 and TNFα, pro-inflammatory cytokines commonly associated with depressive disorders, were found to be increased in cultured neurons, especially after costimulation." (PMID 24391741, 2013). "For example, increased levels of IL-6 are associated with neuropsychiatric conditions, such as depression and Alzheimer’s disease." (PMID 22695063, 2012). "These authors also performed a haplotype analysis with the polymorphisms linked to rs12150214 and found that this region of the SLC6A4 gene was associated with not only depression but also elevated IL-6 levels in the study subjects." (PMID 22911682, 2012). "A single study has reported an association between depression and elevated plasma IL-6 and soluble IL-6 receptor (sIL-6R)." (PMID 22490187, 2012). "Elevated IL-6 plasma levels in particular seem to be associated with major depression in pancreatic cancer patients and tumor cells can influence production of serotonin receptor antibodies active in central nervous system." (PMID 20961421, 2010). "A recent meta-analysis on inflammatory markers in depressed patients has confirmed a consistent positive association between depression and IL-6, and IL-1 and the acute phase protein CRP levels in peripheral blood." (PMID 20161799, 2010). "Associations between IL-6 and depression, vital exhaustion and feeling of hopelessness have also been previously reported." (PMID 20137075, 2010). "Increased circulating levels of IL6 observed during IFNα therapy are associated with symptoms of depression and high levels of IL6 prior to treatment are predictive of depression during IFN treatment." (PMID 27713294, 2010). "Musselman first, reported that higher than normal plasma Il-6 levels were associated with a diagnosis of major depression in a small sample of cancer patients." (PMID 17288583, 2007). "Interleukin‐6 (IL‐6), tumor necrosis factor‐alpha (TNFα), and interleukin‐1 beta (IL‐1β) are three significant cytokines that have been widely investigated concerning the causes of major depressive disorder." (PMID 41479745, 2026). "Meanwhile, a population-based longitudinal study indicated that elevated IL-6 level in childhood was associated with an increased risk of depression, and a systematic review also revealed that patients with melancholic depression exhibit higher peripheral IL-6 level compared to controls." (PMID 41491244, 2026).
depression (continued). "Elevated levels of inflammatory markers such as C-reactive protein and interleukin-6 have been associated with depression, and these markers may underlie the link between the PINI and mortality outcomes." (PMID 40718002, 2025). "IL-6 has been implicated in neurogenesis and synaptic plasticity, with its dysregulation being linked to cognitive dysfunction in mental illnesses such as depression." (PMID 39861166, 2025). "In separate linear regression models that adjusted for multiple covariates, higher levels of IL-6 and IL-8 were associated with increasing levels of depressive symptoms, with the odds of meeting criteria for clinical depression being nearly 2.5 times greater with every unit (pg/dL) increase in IL-8." (PMID 39902492, 2025). "Two pro-inflammatory cytokines that have been consistently linked to the pathophysiology of depression—particularly of TRD—are IL-6 and IL-8; their elevated levels have been associated with increased neuroinflammation, impaired neuroplasticity, and resistance to standard antidepressant therapies." (PMID 40498007, 2025). "Elevated IL-6 levels may also be associated with psychological complications, the occurrence of anxiety or depression, which negatively affect rehabilitation outcomes, the effectiveness of neurotrophic agents, and even mortality in patients with AIS." (PMID 40305179, 2025). "Immune dysregulation, such as defective antigen presentation caused by interleukin 6 (IL-6) or an IL-1β-mediated hemophagocytosis-like syndrome, may play a role in depression." (PMID 41011169, 2025). "In contrast, the natural oral microbiota may modulate the immune system through metabolites (e.g., short-chain fatty acids) and inhibit the transmission of peripheral inflammatory factors (e.g., IL-6) to the brain, thereby reducing the risk of depression." (PMID 40474156, 2025). "Evidence from animal and human clinical studies suggest that elevated levels of IL-6 may interfere with the normal physiological response to stress, and cause depression through activation of the hypothalamic-pituitary-adrenal axis." (PMID 40313235, 2025). "Depression is a multifaceted disorder caused by neuroinflammation, which is mainly demarcated by a significant increase in proinflammatory cytokines, including interleukin-1β (IL-1β), interleukin-6 (IL-6), and tumor necrosis factor-α (TNF-α)." (PMID 40487411, 2025). "For instance, higher levels of IL-6 are associated with increased connectivity within the default mode network, which has been linked to excessive rumination and self-referential cognitions in depression." (PMID 41210298, 2025). "Although previous studies have reported in depression, association with elevated peripheral inflammation particularly IL-6, whether IL-6 has pro- or anti-inflammatory effects in the disease remains unclear." (PMID 40179065, 2025). "Higher IL-6 was associated with worse trajectories of depression symptoms across the life course." (PMID 39865800, 2025). "IL-6 was associated with depression in people experiencing the stressful events." (PMID 39867847, 2025). "Causal evidence also comes from RCTs showing anti-inflammatory treatment for chronic inflammatory conditions improves depressive symptoms independent of improvement in physical symptoms and other MR studies suggesting putative causality of IL-6 on major depressive disorder." (PMID 39865800, 2025). "While some studies suggest that daily supplementation may be more effective for neuropsychiatric symptoms such as anxiety and depression, bolus administration has been linked to greater reductions in inflammatory markers, particularly IL-6." (PMID 40429727, 2025). "Taking major depression as an example, animal research showed depression-like behavior can could be caused by IL-6 and IL-1." (PMID 39757257, 2025). "Elevated IL-6 levels were similarly associated with anhedonia (OR = 1.30), sleep disturbances, and appetite changes, suggesting a neurovegetative profile of inflammation-related depression." (PMID 41373439, 2025).